BIRC5 (baculoviral IAP repeat containing 5)
Diseases named in the same sentence as BIRC5 in open-access papers (continued):
Sharing a sentence is not in itself a finding about the gene and the disease.
tumor (continued). "The results revealed that EIF4EBP1, RIMKLA, and BIRC5 upregulated in tumor tissues, while other genes downregulated in normal tissues, which is consistent with the results in TCGA-KIRC datasets." (PMID 40591061, 2025). "In this study, BIRC5/Survivin RNAi using propylene imine conjugated antibody prevented the growth of tumor cells that express PSCA antigen on their surface." (PMID 38627732, 2024). "Specifically, we seek to investigate the relationship between BIRC5 expression and tumor subtypes, clinical prognosis, and molecular pathways." (PMID 39703228, 2024). "The tumor sizes in the BIRC5-206 knockdown group were notably larger than those in the control group, as demonstrated by in vivo bioluminescence imaging." (PMID 39308922, 2024). "Survivin (BIRC5) serves as a significant cancer biomarker, granting tumor cells enhanced survival capabilities by suppressing apoptosis." (PMID 38892366, 2024). "BIRC5, involved in positive regulation of the cell cycle response, is highly expressed in T cells and various tumor tissues." (PMID 38658744, 2024). "HE staining revealed that the lung tissue in the control group maintained normal and well-structured architecture, whereas the lung tissue in the BIRC5-206 knockdown group exhibited disrupted structures due to tumor cell infiltration." (PMID 39308922, 2024). "Tumour targets were enriched for genes involved in cell proliferation, G1/S transition, and inhibition of apoptosis; for example, BIRC5 activated by ITGB1 from the tumour and stroma." (PMID 38890455, 2024). "The findings indicate that BIRC5 mRNA levels are generally elevated in 33 tumor types compared to normal tissues, with significant protein overexpression in most cancerous tissues." (PMID 39703228, 2024). "Most tumors exhibited four to five immune subtypes, suggesting a strong link between BIRC5 and tumor immunity." (PMID 39703228, 2024). "HMGB2 in POSTN+ fibroblasts is predicted to bind to PLD2, LRP5, MYLK, and CD44 on tumor cells, regulating downstream genes, including BIRC5, CCNA2, CCNB1, CCNB2, CDC20, and MKI67, which are related to the cell cycle." (PMID 38519500, 2024). "It has been shown that inhibition of BIRC5 can induce tumor cell apoptosis and enhance sensitivity to chemotherapeutics or other apoptotic stimuli." (PMID 40552132, 2024). "Further, age and race seem to be important factors contributing to BIRC5 levels, even after adjusting for tumor characteristics." (PMID 38515208, 2024). "BIRC5 can also promote tumor resistance to broad-spectrum chemotherapy drugs, radiation insensitivity, and lead to poor prognosis." (PMID 38556560, 2024). "independently established that the overexpression of BIRC5 serves as a significant factor associated with a poor prognosis in LUAD, promoting tumour development via the regulation of immune checkpoint expression, leading to immune evasion." (PMID 38429900, 2024). "Birc5 was a potential biomarker and inducer of intratumor infiltration of MDSCs, which led to T cell exclusion or dysfunction in tumor immune microenvironment, consequently resulting in reduced response to ICIs in HCC." (PMID 37326143, 2023). "In immune infiltration analysis, the results indicated that patients with high BIRC5 expression had lower CD8 T cell infiltration in tumor samples." (PMID 37077837, 2023). "Survivin, also known as BIRC5, is a protein that promotes tumor cell proliferation and inhibits apoptosis." (PMID 38067304, 2023). "Based on these results, expression levels of BIRC5, HIF1A, and FLT4 associated with primary NSCLC tumor progression and metastasis were compared to normal samples." (PMID 37509650, 2023). "According to the flow cytometry results, the inhibition of BIRC5 expression increased tumor cell apoptosis and decreased HNSCC anoikis resistance." (PMID 37547764, 2023). "Notable changes were observed in the expression levels of BIRC3 and BIRC5 across different tumor stages." (PMID 37781078, 2023).
tumor (continued). "Studies have shown an increased expression level of BIRC5 in GC, which was correlated with the depth of tumor invasion, distant metastasis, and TNM stage of GC." (PMID 36863706, 2023). "The selective inhibition of CDK1 by small-molecule inhibitors, purvalanol or roscovitine, causes the suppression of the apoptosis protein BIRC5 (survivin), which is essential for the survival of MYC-driven tumor cells." (PMID 37443779, 2023). "Our results showed that high expression levels of BIRC5, FLT, and HIF1A were more clearly associated with primary NSCLC tumor progression and metastasis than normal samples." (PMID 37509650, 2023). "At the same time, the immune analysis showed that BIRC5 was related to the tumor microenvironment, especially CD8 T cell infiltration." (PMID 37077837, 2023). "YM155, a BIRC5 inhibitor, induced a potent tumor-suppressive effect in the three types of RCC cells and xenograft models." (PMID 38203388, 2023). "We selected BIRC5 as BIRC5 was significantly increased by more than 2-fold in tumors compared with non-tumor samples; similar patterns were observed in paired analysis of the 3 major RCC subtypes." (PMID 38203388, 2023). "Several studies have reported that miRNAs, small‐molecule inhibitors, antisense oligonucleotides, and peptide‐based immunotherapy can significantly downregulate BIRC5 expression, consequently inhibiting tumor cell growth." (PMID 38112021, 2023). "The oncogene, anti-apoptotic factor BIRC5, which was found to be targeted by different inhibitors, induced tumor cell apoptosis and cell cycle arrest." (PMID 37958642, 2023). "Survivin (BIRC5), a member of the inhibitor of the apoptosis family, can promote cell division and tumor proliferation." (PMID 37679418, 2023). "Birc5 expression was related to immune cell infiltration in the tumor microenvironment of several tumors." (PMID 37326143, 2023). "Immunohistochemical staining confirmed that Birc5 was overexpressed in the nucleus of HCC tumor cells." (PMID 37326143, 2023). "Additional lv‐BIRC5 increased the volume and weight of tumours in presence of lv‐miR‐126‐5p after radiotherapy." (PMID 35322532, 2022). "Although publicly available TCGA data are useful for explorative pan-cancer studies, these findings need to be examined further in specific tumor types at the protein level to assess the clinical utility of BIRC5/Survivin." (PMID 35331169, 2022). "In the future, we will pay more attention to the function of BIRC5 in tumor metastasis and tumor microenvironment regulation of LGG." (PMID 35309512, 2022). "The nomogram predicts the 1, 3, 5-year OS in the TCGA-LUAD cohort using age, T, M, N classification, pathologic stage, residual tumor, and BIRC5 expression." (PMID 36046648, 2022). "In fact, BIRC5 was significantly upregulated in the tumor group compared with the control group (FC = 2.45, p value < 0.01) and its expression level showed a significantly positive correlation with that of RHOA (r = 0.56, p value = 0.001)." (PMID 35406376, 2022). "Of note, our original prediction was based on TCGA and GEO datasets analyses, we found BIRC5 was strongly correlated with higher tumor grade of LSCC." (PMID 35178302, 2022). "BIRC5, an immune-related gene was found to be highly expressed in different tumour types and promotes cell proliferation." (PMID 35552415, 2022). "YAP/TAZ‐activated genes involved in cell cycle progression and survival (BIRC5) that are increased with OSCC tumour grade or stage were also identified here." (PMID 35000271, 2022). "With the data from UALCAN dataset showed that BIRC5 had higher expression levels in advanced LSCC tumor grade." (PMID 35178302, 2022). "The multiplex ddPCR assay was developed using tumor cell lines positive for the tumor associated antigens (TAA: WT1, PRAME, BIRC5), with homeostatic ABL1." (PMID 36248870, 2022).
tumor (continued). "ReactomeFIViz enrichment analysis in Cytoscape showed an association of seven (EDNRB, CDKN2A, VEGFD, FOS, GNG11, TGFBR2, and BIRC5) of the forty-four nodes of the LC-BC CCPs with signaling pathways related with the acquisition of tumor characteristics." (PMID 36101460, 2022). "Our study also decided to test the mRNA levels of BIRC5 (survivin), which acts as a prognostic biomarker in neoplastic diseases, indirectly inhibits apoptosis, and promotes cell proliferation." (PMID 35740420, 2022). "A two-gene signature based on KLK3 and BIRC5 expression was evaluated for predicting circulating tumour cell (CTC) levels in metastatic castration-resistant PCa (mCRPC) that produced an AUC of 0.74 from a set of 29 mCRPC and 19 healthy individuals." (PMID 36033512, 2022). "In our research, PC cell lines and a PC xenograft tumor mice model were utilized to investigated the expression and function of BIRC5 in PC development." (PMID 35461228, 2022). "So far, there were numerous evidence indicated that hyperactivation of BIRC5 was occurred in various tumor diseases and played an oncogenic role in carcinogenesis." (PMID 35461228, 2022). "Previous studies have confirmed that the five autophagy-related genes (BIRC5, SQSTM1, HDAC1, RHEB, and ATIC) are associated with tumor proliferation, apoptosis, and resistance to anticancer agents in HCC patients." (PMID 35573678, 2022). "Five variables (LINC01089, RGS11, MXD3, BIRC5, and RAB30) of Sig27var25 are risk factors of poor OS and three of them remain risk factors of fatality after adjusting for age at diagnosis and tumor stages." (PMID 35681785, 2022). "RUNX1 knockdown clearly caused an increase in p21 and a decrease in BIRC5 in the A172, KALS-1 and LN229 cell lines, suggesting that these genes represent targets of RUNX1 and strongly influence tumour suppression by causing apoptosis and cell cycle arrest." (PMID 36085167, 2022). "The ratio of tumor-infiltrating CD8 T cells (TILs) in the Lv-BIRC5 group was significantly lower than that in the control group, just as was the proportion of functional IFN-g secreted by TILs." (PMID 36046648, 2022). "We used PC cell lines (Penl1 and Penl2) and constructed a PC xenograft mice model to explore the effects of the silencing of BIRC5 on proliferation, migration, invasion and tumor growth, as well as survival of mice." (PMID 35461228, 2022). "Exportin-1 (CRM1) is critical for CPC binding to centromeres when interacting with BIRC5, and thus, modulating the heterodimeric BIRC5/CRM1 complex, a number of pathogenic processes, including tumor cell proliferation, can be affected." (PMID 35053254, 2022). "The results indicated that BIRC5 expression was related with advanced tumor grade and differentiation." (PMID 35178302, 2022). "Taken together, our data revealed that BIRC5 silencing inhibited aggravation of PC cell processes and tumor development induced by ITM." (PMID 35461228, 2022). "Consistently, our study indicated that IFN-γ dramatically promoted the proliferation, migration and invasion of PC cells, as well as tumor growth in vivo, while BIRC5 knockdown reversed these effects." (PMID 35461228, 2022). "The lowest concentration of phytoestrogen also increased the expression of the BIRC5 gene in the tumor line, while concentrations of 20 and 50 μM decreased it." (PMID 36293214, 2022). "BIRC5 was shown to be significantly expressed in the triple-negative subtype of BC, and BIRC5 suppression reduced the growth of BC cells, suggesting that BIRC5 functions as a tumor driver." (PMID 36358602, 2022). "In the independent GC dataset, BIRC5 was highly expressed in the tumor group compared to the control group, and its expression level was substantially correlated with that of RHOA." (PMID 35406376, 2022). "The remaining 3 genes (CBX7, TOP2A and BIRC5) filled the gaps of tumour cell regulation in stem cell, epigenetic, genomic instability, proliferation and differentiation." (PMID 35326543, 2022).
tumor (continued). "The morphological size, tumor volume and weight in the BIRC5 silencing group were significantly lower than those in the model group; IFN-γ dramatically increased these indexes of PC xenograft tumor in mice while BIRC5 also weaken the effect of IFN-γ in vivo." (PMID 35461228, 2022). "The hub genes TOP2A, CDK1, and BIRC5 formed the top cluster with expression in 80–90% of the tumours." (PMID 36345011, 2022). "RNA expression levels were found to be higher for tumor samples with higher amplification of BIRC5 (P < 2.2e− 16)." (PMID 35331169, 2022). "Stages two and three of the tumors had increased transcript expression of BIRC5 significantly compared to normal, as well as stages one and four of the tumors, and BIRC5 remained overexpressed (p < 0.001) throughout tumor stages." (PMID 36358602, 2022). "An enhancement of miR‐126‐5p and KLF2 while reductions in EZH2 and BIRC5 were seen in tumour tissues of nude mice treated with X‐ray alone or combined with lv‐miR‐126‐5p." (PMID 35322532, 2022). "The data collected in this investigation showed that BIRC5 functioned consistently as a potential tumor-enhanced gene or as a prognostic marker." (PMID 36358602, 2022). "Transcript levels of β-catenin target proteins such as Ccnd2, CDKN2A, and BIRC5 are known to be increased in tumor patients." (PMID 36209344, 2022). "For NIR (Near-Infrared) imaging, IOMNP cores coated with dextran are triple-conjugated to peptide sequences (which selectively bind to tumor-specific antigen uMUC-1), the dye Cy5.5, and siRNA molecules (that binds the tumor-specific antiapoptotic gene BIRC5)." (PMID 36091772, 2022). "Third, we did not conduct the in vivo experiments to validation the function of BIRC5 in the tumor metastasis and tumor microenvironment regulation of LGG." (PMID 35309512, 2022). "By establishing a new analysis pipeline, we unraveled 85 prime miRNA–mRNA interactions supporting the downregulation of candidate tumor suppressors and the upregulation of bona fide oncogenes such as survivin (BIRC5) in ATC." (PMID 34885022, 2021). "This study aimed to analyze the relationship between the expression level of BIRC5 in different tumors and patient prognosis, clinical parameters, and its role in tumor immunity." (PMID 33431968, 2021). "BIRC5 is a very promising and well-studied therapeutic target because of its preferential expression in tumor cells of adult individuals." (PMID 33413657, 2021). "Several studies have shown that vaccines targeting BIRC5 have promising anti-tumor effects through different approaches." (PMID 33431968, 2021). "Consistently, we found that BIRC5 expression levels were significantly higher in tumor tissues than in normal tissues." (PMID 34925455, 2021). "In this work, we report on the targeted delivery of a therapeutic siRNA specific for BIRC5/Survivin in vitro and in vivo to tumor cells expressing the surface marker prostate stem cell antigen (PSCA)." (PMID 34066833, 2021). "Herein, we found that the overexpression of BIRC5 was significantly correlated with tumor stage, age, gender, smoking habits, and nodal metastasis status in normal tissues." (PMID 34804966, 2021). "BIRC5, on the contrary, is commonly considered an anti-apoptotic molecule, promoting cell division and tumor progression and it is widely regarded as potential therapeutic target." (PMID 33413657, 2021). "The expression of the tumor markers in both models was similar, with an increase in the mRNA levels of Ly6d, Afp, Gpc3, Birc5, and Lyve1 being higher in DEN-treated WT mice compared to MUP-uPA, while that of Cd44 was comparable in both models." (PMID 34439245, 2021). "Then, we analyzed the transcription levels of BIRC5 by tumor stage, patients’ age, patients’ gender, smoking habits, and nodal metastasis status for LUSC and LUAD." (PMID 34804966, 2021). "In this study, we observed the expression, interaction, and roles of CXCR4 and BIRC5 in GBM tumour samples in relation to epigenetics, stemness, and immunity." (PMID 34685742, 2021).
tumor (continued). "The estimate package was used to analyze the immune score and stromal score of each tumor sample and determine the relationship between BIRC5 expression level, immune score, and stromal score in 33 tumors." (PMID 33431968, 2021). "The prognosis of each tumor sample in the TCGA database was analyzed to determine the effect of BIRC5 expression levels on the prognosis of patients with different tumors." (PMID 33431968, 2021). "In the Oncomine database, we found that BIRC5 was highly expressed in 18 of the 20 tumor tissues included." (PMID 33431968, 2021). "BIRC5 is up-regulated in a variety of tumor tissues, and closely related to the metastasis, recurrence, and poor prognosis of these tumors." (PMID 34112092, 2021). "More recent researches have shown that BIRC5 possesses an important role in tumorigenesis, tumor progression and patient prognosis, suggesting that BIRC5 and its related genes have a potential application in HCC diagnosis and prognosis." (PMID 34112092, 2021). "BID, NAMPT, and BIRC5 were detected with the same results in tumor tissues and with adjacent normal kidney tissues, while CANX was not significantly different." (PMID 34988121, 2021). "STAT3 acts astranscriptional regulator of a variety of tumor-promoting genes such asVEGF, c-MYC, CCND1 (cyclinD1), BIRC5 (survivin), which are involved in tumor development andprogression." (PMID 33749701, 2021). "The upregulation of BIRC5 in tumors was significantly and positively correlated with the level of activated tumor immune cells." (PMID 33431968, 2021). "Surprisingly, the promoter methylation level of BIRC5 was found to be increased in tumor samples, which appears to go against its expression pattern." (PMID 33671201, 2021). "In further analysis, we divided tumor samples into two groups based on the median expression of BIRC5." (PMID 33431968, 2021). "BIRC5 is a negative regulatory protein that inhibits tumor cell apoptosis and promotes cell proliferation." (PMID 33778011, 2021). "The long-term 27-years survival data were available for VGR-BC and revealed that zero BIRC5/survivin protein levels in the tumor samples carried the important message for our understanding of the prognostic survival differences." (PMID 34064473, 2021). "Immune infiltration analysis suggested that BIRC5 expression was significantly inversely correlated with tumor-infiltrating cell numbers and immune biomarker expression in NSCLC." (PMID 34804966, 2021). "Tumors from MUP-uPA mice fed the HFHC diet exhibited an increased expression of tumor markers Ly6d, Cd44, Golm1, and Birc5, as well as higher levels of the proliferation marker Mki67." (PMID 34439245, 2021). "The available data concerning BIRC5 are, on the contrary, rather homogeneous and point to a tumor promoting role for this IAP." (PMID 33413657, 2021). "High BIRC5 expression in tumor cells correlates with cell division, apoptosis inhibition, chemoresistance, and stemness." (PMID 33311446, 2020). "Collectively, these results indicate that high tumor expression levels of both EGFR and BIRC5 are associated with more rapid development of liver and lung metastases in patients compared to tumors with low expression of one or both of these genes." (PMID 32001757, 2020). "We identified six TAA protHLAIp that were exclusively detected in the tumor tissue of C3N-02289 (BIRC5, TERT, FAP, SPAG4, MAGEA9, and BCL2L1)." (PMID 32157095, 2020). "In MCF-7 cell lines, combination therapy enhanced the downregulation of essential components of the cell cycle (HMMR, AURKB, BIRC5) that control proliferative activities and tumour growth alongside downregulation of the anti-senescence markers FOXM1 and E2F1." (PMID 32787886, 2020). "Analysis of Survivin_oHSV replication showed that the ICP4 conditioning by Survivin/BIRC5 promoter mediated up to 3 orders of magnitude of selectivity for cancer cells as compared to non-tumour MRC5 fibroblasts." (PMID 32152425, 2020).